YBX1 (Y-box binding protein 1)
Diseases named in the same sentence as YBX1 in open-access papers (continued):
Sharing a sentence is not in itself a finding about the gene and the disease.
liver fibrosis (11 papers, 2014 to 2025). "Previous studies have demonstrated that YBX1 is up-regulated in the fibrotic liver, and its knockdown ameliorates hepatic fibrosis in mouse models 25,26." (PMID 40083711, 2025). "Besides, TGF-β1 treatment induces YBX1 nuclear translocation in hepatic progenitor cells (HPCs) and promotes the proliferation of HPCs in liver fibrosis." (PMID 40346063, 2025). "A subsequent study showed that YBX1 promotes HPCs proliferation, EMT, and ECM deposition during liver fibrosis." (PMID 40346063, 2025).
myeloid leukemia (11 papers, 2021 to 2025). A clonal proliferation of myeloid cells and their precursors in the bone marrow, peripheral blood, and spleen. "YBX1 has also been demonstrated to be specifically required for maintaining myeloid leukemia cell survival." (PMID 39849644, 2025). "Especially, RNA‐binding protein, such as YBX1 that is necessary for tumour progression and metastasis, including the survival of myeloid leukaemia cells, is considerably upregulated on BM‐MSCs treated with MV4‐11 sEVs." (PMID 38499475, 2024). "YBX1 is a multifunctional RNA-binding protein that can act as a “reader” for m5C, which is crucial in regulating the survival of myeloid leukemia cells and the occurrence and development of AML." (PMID 37007137, 2023). "A recent study reported a role of YBX1 in interacting with the readers of N6-methyladenosine (m6A), another RNA modification, and stabilizing m6A-modified RNA for maintaining myeloid leukemia cell survival." (PMID 36642732, 2023). "YBX1 is significantly upregulated in myeloid leukemia, and deletion of YBX1 dramatically induces apoptosis, promotes differentiation, and impaired leukemic capacity." (PMID 34753494, 2021). "Notably, IGF2BP3 has been reported to stabilize Myc transcripts by cooperating with YBX1 in an N6-methyladenosine (m6A)-dependent manner in myeloid leukemia cells." (PMID 38561347, 2024). "This may provide a theoretical basis for therapy targeting YBX1 in myeloid leukemia and could demonstrate its role in m6A modification." (PMID 37007137, 2023). "Indeed, a recent study reported that YBX1 is required for maintaining myeloid leukemia cell survival by regulating BCL2 stability in an m6A-dependent manner." (PMID 35109938, 2022). "More recently, our colleagues reported that YBX1 contributes to myeloid leukemia cell survival." (PMID 34753494, 2021). "Therefore, the selective role of YBX1 in cancer suggests that it may be a promising target for more comprehensive research and treatment of myeloid leukemia." (PMID 38255791, 2024).
head and neck squamous cell carcinoma (10 papers, 2020 to 2024). A squamous cell carcinoma that arises from any of the following anatomic sites: lip and oral cavity, nasal cavity, paranasal sinuses, pharynx, larynx, and salivary glands. "Another study revealed that LNCAROD can bind with HSPA1A and YBX1 and promoted cancer progression in head and neck squamous cell carcinoma." (PMID 37597098, 2023). "LNCAROD enhanced its mRNA stability through m6A methylation modification, and a complex with HSPA1A and YBX1 promoted the progression of head and neck squamous cell carcinoma." (PMID 34336856, 2021). "Moreover, we found that high expression of YBX1 predicts unfavorable overall survival of head and neck squamous cell carcinoma (HNSCC) patients." (PMID 33976741, 2021). "Likewise, METTL3- and METTL14-mediated m6A modification of LncAROD enhanced its stability and promoted ternary complex formation with HSPA1A and YBX1, driving progression in head and neck squamous cell carcinoma." (PMID 34458149, 2021). "Similarly, LNCAROD is up-regulated by METTL3/METTL14 in head and neck squamous cell carcinoma (HNSCC) and impels its tumorigenicity through preventing YBX1 from degradation." (PMID 33754077, 2021).
neuroblastoma (10 papers, 2015 to 2026). Neuroblastoma (NB) is the most common solid, extracranial childhood tumor. "For example, YBX1 promotes cell proliferation, invasion, and drug resistance through NF-κB signaling pathway in human neuroblastoma." (PMID 41513625, 2026). "Coincidentally, the highest SNHG1 binding protein score in neuroblastoma also includes YBX1 (and also HnRNPL and MATR3), where the role of HnRNPL interacting with SNHG1 in PCa has been demonstrated." (PMID 41507135, 2026). "In a recent study, YBX1 was also found to exert important activities in the NF-κB pathway in human neuroblastoma cells." (PMID 31481087, 2019). "Moreover, YBX1 enhances cisplatin sensitivity in neuroblastoma through this pathway." (PMID 41507134, 2026).
pancreatic ductal adenocarcinoma (10 papers, 2022 to 2025). An infiltrating adenocarcinoma that arises from the epithelial cells of the pancreas. "The possible reduction of YBX1 cytoplasmic availability inhibits proliferation of myeloid differentiation-inducing apoptosis and decreases the expression of cyclin D1 and cyclin E1 associated with pancreatic ductal adenocarcinoma cell growth." (PMID 36066672, 2022). "m5C methylation reader YBX1 is related to PD-L1 expression levels in pancreatic ductal adenocarcinoma." (PMID 39372415, 2024). "The m5C methylation reader YBX1 is found to be positively related to the presence of NK cells in cases of pancreatic ductal adenocarcinoma." (PMID 39372415, 2024). "CircFOXK2 promoted pancreatic ductal adenocarcinoma (PDAC) progression by interacting with YBX1 and hnRNPK proteins to upregulate the expression of NUF2 and PDXK oncogenes." (PMID 38890620, 2024). "The m5C methylation reader YBX1 is related to activated dendritic cells in pancreatic ductal adenocarcinoma." (PMID 39372415, 2024). "Recently, a circRNA derived from FOXK2 (has_circ_0000816) has been found to promote the growth and metastasis of pancreatic ductal adenocarcinoma by sponging miR-942 and directly binding YBX1 and hnRNPK." (PMID 36922872, 2023). "Through the GSK3B/Cyclin D1/Cyclin E1 pathway, YBX1 depletion induces apoptosis and decreases cyclin D1 and cyclin E1 protein expression, resulting in a reduction in Pancreatic Ductal Adenocarcinoma growth." (PMID 36066672, 2022). "Moreover, evidence has demonstrated that the nuclear translocation of YBX1 promotes mucin expression, thereby contributing to the survival of pancreatic ductal adenocarcinoma cells within TME." (PMID 38698857, 2024). "The m5C methylation reader YBX1 is positively correlated with CD4+ memory T cells, CD8+ T cells, type 1 and type 2 T helper cells in pancreatic ductal adenocarcinoma." (PMID 39372415, 2024).
esophageal cancer (9 papers, 2018 to 2025). A primary or metastatic malignant neoplasm involving the esophagus. "Both NSUN2 and YBX1 are markedly upregulated in esophageal cancer tissues compared to adjacent normal tissues." (PMID 40114967, 2025). "To explore the potential role of YBX1 in esophageal cancer, we first investigated the expression profile of YBX1 based on public datasets and further validated it using our own clinical ESCC samples by western blotting." (PMID 38566431, 2024). "YBX1 expression had been observed not only in endothelial cells but in esophageal cancer cells as well." (PMID 30143675, 2018). "YBX1 overexpression further promotes the growth and metastasis of esophageal cancer." (PMID 40114967, 2025). "Indeed, we found that the mRNA expression levels of ILF2 and YBX1 were upregulated in esophageal carcinoma tissues compared to normal controls in GEPIA dataset." (PMID 36717549, 2023).
esophageal squamous cell carcinoma (9 papers, 2015 to 2025). Esophageal squamous cell carcinoma (ESCC) is a type of esophageal carcinoma (EC) that can affect any part of the esophagus, but is usually located in the upper or middle third. "Recent studies have found that YBX1 is aberrantly overexpressed in esophageal squamous cell carcinoma (ESCC), with a significant correlation between high YBX1 levels and poor patient survival." (PMID 40370440, 2025). "For example, YBX1 interacts with SOX2 mRNA to enhance its stability in esophageal squamous cell carcinoma." (PMID 40703976, 2025). "In esophageal squamous cell carcinoma (ESCC), YBX1-mediated linc02042 and c-MYC form a new positive feedback loop, enhancing the stability and translation efficiency of c-MYC mRNA and promoting tumorigenesis and metastasis." (PMID 40799245, 2025). "However, the precise role and potential mechanism of Y‐box‐binding protein 1 (YBX1) in esophageal squamous cell carcinoma (ESCC) remains unclear." (PMID 38566431, 2024).
lymph node metastasis (9 papers, 2016 to 2023). "Positive associations were found between tumour size and YBX1 RNA, and lymph node metastasis with c-MYC RNA levels." (PMID 31461477, 2019). "Further study indicated that HUMT exerted its function by recruiting YBX1 protein to the promoter region of FOXK1 and promoted its transcription, activating lymph node metastasis-related Akt/mTOR/VEGFC signaling." (PMID 32138762, 2020).
medulloblastoma (9 papers, 2011 to 2025). A malignant, invasive embryonal neoplasm arising from the cerebellum. "As these genes appear to be associated with an inflammatory response, this enables YBX1 to indirectly repress inflammatory response and apoptosis in medulloblastoma." (PMID 32585856, 2020). "They show that targeting YBX1 targets stem-like progenitor cells in G3 medulloblastoma reducing self-renewal, proliferation, and tumor growth in vivo." (PMID 40471378, 2025). "Based on a previous publication demonstrating control of PRC2, the methyltransferase responsible for H3K27me3, they assessed the role of the RNA/DNA binding YBX1 in G3 medulloblastoma." (PMID 40471378, 2025). "Depleting YBX1 in both Sonic Hedgehog and Group 3 medulloblastoma not only decreases proliferation but also synergizes with radiation treatment, primarily due to distinct response dynamics." (PMID 38255791, 2024). "To confirm its essentiality in medulloblastomas, we used an siRNA pool of 30 siRNAs targeting YBX1 for the knockdown (KD) of YBX1 in medulloblastoma cell lines DAOY, Med8A (RRID: CVCL_M137) and UW228-3." (PMID 32585856, 2020). "Although Ybx1 promotes the proliferation of medulloblastoma or glioblastoma cancer cells, it suppresses the proliferation and self-renewal of NPCs." (PMID 32792512, 2020). "We here show that YBX1 can also be considered as an oncogene in medulloblastomas and leads to decreased survival of various medulloblastoma cell lines upon knockdown." (PMID 32585856, 2020). "We here analyzed the oncogenic effect of YBX1 in three medulloblastoma cell lines based on RNA-Seq and PAR-CLIP data, revealing important insights into its posttranscriptional functions and its potential target gene network." (PMID 32585856, 2020). "We observed different cellular responses upon YBX1 knockdown in several medulloblastoma cell lines, with significantly altered transcription and subsequent apoptosis rates." (PMID 32585856, 2020). "We considered all eight available medulloblastoma cell lines and found that YBX1 is among the top 20–30% quantile of essential genes among 1621 canonical RBPs targeted in the screen." (PMID 32585856, 2020). "We also set out to define the direct impacts of YBX1 KD in medulloblastoma on posttranscriptional control." (PMID 32585856, 2020). "Among a list of 1220 canonical RBPs represented on the microarray, we found that YBX1 is ubiquitously expressed in medulloblastoma patient samples across all sub-types and ranks among the top expressed RBPs on average." (PMID 32585856, 2020). "YBX1 levels are heightened in medulloblastoma and play a role in promoting proliferation in Sonic Hedgehog-dependent cerebellar granule neuron progenitor cells and medulloblastoma cells." (PMID 38255791, 2024). "Thus, YBX1 acts as an oncogene in medulloblastoma through indirect transcriptional regulation of inflammatory genes regulating apoptosis and represents a promising novel therapeutic target in this tumor entity." (PMID 32585856, 2020). "Here, we show that the posttranscriptional regulator Y-box binding protein 1 (YBX1), a DNA- and RNA-binding protein, acts as an oncogene in medulloblastomas by regulating cellular survival and apoptosis." (PMID 32585856, 2020). "This work will provide a deeper understanding of the molecular insights of YBX1 in oncogenesis and lay the foundation for the continued development of novel therapeutic strategies for MYC-driven medulloblastoma by harnessing their discovery of a MYC-YBX1-PRC2 axis." (PMID 40471378, 2025). "However, there was no clustering of the medulloblastoma subgroups SHH, WNT, group 3 and group 4 based on YBX1 expression." (PMID 32585856, 2020).
mesothelioma (9 papers, 2019 to 2026). A usually malignant and aggressive neoplasm of the mesothelium which is often associated with exposure to asbestos. "Entinostat was found to decrease the deacetylation of Y-box-binding protein 1 (YB-1), a pro-tumorigenic nucleic acid-binding protein upregulated in mesothelioma, causing the reduction of mesothelioma cell proliferation." (PMID 40918456, 2025). "Specifically, YBX1 emerged as significant risk factors for adrenocortical carcinoma (ACC), low LGG, liver hepatocellular carcinoma (LIHC), mesothelioma (MESO)." (PMID 38698857, 2024).
viral infection (9 papers, 2014 to 2023). "Remarkably, YBX1, which was identified to bind Motifs3 and Motif6, was found to be associated with viral infections, including SARS-CoV-2 and Zika, and previous experiments have shown that knockout of this gene can reduce the infection intensity." (PMID 36970680, 2023). "After 2 weeks of HFD feeding, we found that iWAT from mice infected with Ad-EGFP or Ad-YBX1 robustly expressed EGFP, indicating the success of virus infection and YBX1 overexpression." (PMID 36642732, 2023). "Interestingly, no decrease in HBV infection was observed when YBX1 knockdown in HBV-infected HepG2-NTCP cells was achieved after virus infection when the initial cccDNA pool is already established." (PMID 36591611, 2022).
myocardial infarction (8 papers, 2019 to 2025). Gross necrosis of the myocardium, as a result of interruption of the blood supply to the area, as in coronary thrombosis. "In a mouse model of myocardial infarction, the deletion of Ybx1 has been shown to enhancein vivo reprogramming, leading to improved cardiac function." (PMID 40629906, 2025). "Y-box-binding protein 1 (Ybx1) is an essential transcriptional protein in myocardial proliferation after myocardial infarction, which acts as a substrate for Nedd4L and can bind to Nedd4L for degradation." (PMID 35429991, 2022). "The transcription factor Y-box binding protein 1 (YB-1) is upregulated in the early phase after myocardial infarction in rats and may contribute to post-infarct remodeling processes." (PMID 38203580, 2023). "EC up-regulated ybx1 after MTZ treatment, which has been shown to be beneficial for cardiac repair after myocardial infarction in mice." (PMID 37155312, 2023). "Loss of superenhancer-regulated circNfix promotes cardiac regenerative repair and functional recovery after myocardial infarction by suppressing Ybx1 ubiquitin-dependent degradation and increasing miR-214 activity and thus may be a promising strategy for improving the prognosis after MI." (PMID 30947518, 2019).
renal carcinoma (8 papers, 2014 to 2026). A carcinoma arising from the epithelium of the renal parenchyma or the renal pelvis. "To investigate YBX1’s role in renal cancer progression, we assessed its effects on cell proliferation, migration, and invasion." (PMID 41507134, 2026). "Y-box binding protein 1 B1 (YB1), a member of the cold-shock domain protein family, has been reported to be highly expressed in a variety of malignancies including renal cancer." (PMID 32814829, 2020). "Renal cancer cell lines, human embryonic kidney cells, and clinical samples were analyzed to investigate the functional role of YBX1 in RCC metastasis." (PMID 31481087, 2019). "In addition, CD4+ T cells promote renal cancer cell proliferation by regulating YBX1, and MDSCs accumulate in various tumors, promoting vascular survival and improving tumor immunity." (PMID 35571068, 2022). "Importantly, our genomic expression profiles suggested that gastric tumor tissues exhibit aberrant overexpression of SPP1, which has been shown to be upregulated by YBX1 in renal cancer cells." (PMID 34758833, 2021). "Additionally, YBX1 is capable of interacting with G3BP1 to promote SPP1 upregulation, resulting in renal cancer invasion and metastasis." (PMID 34758833, 2021).
cholangiocarcinoma (7 papers, 2022 to 2026). A carcinoma that arises from the intrahepatic biliary tree (intrahepatic cholangiocarcinoma) or from the junction, or adjacent to the junction, of the right and left hepatic ducts (hilar cholangiocarcinoma). "In cholangiocarcinoma patients, the m5C-modified functional lncRNA NKILA (NF-kappa B interacting lncRNA), which is recognized and stabilized by YBX1, is associated with advanced TNM stage and poor prognosis." (PMID 37325635, 2023). "In cholangiocarcinoma, KIF14 binds to the G3BP1/YBX1 complex, leading to the activation of the NF-κB pathway." (PMID 41507134, 2026). "In cholangiocarcinoma, the m5C methyltransferase NSUN2 interacts with the lncRNA NKILA to increase its m5C level and promote its interaction with YBX1." (PMID 36333719, 2022).
Ewing sarcoma (6 papers, 2019 to 2024). A small round cell tumor that lacks morphologic, immunohistochemical, and electron microscopic evidence of neuroectodermal differentiation. "In contrast, the interactions between DHX9 and YBX1, proteins with known roles in Ewing sarcoma, were greatly attenuated in the presence of high salt and RNase A." (PMID 36793594, 2023). "A multifunctional protein EWS (Ewing sarcoma), coupled with its binding partner Y-box binding protein 1 (YBX1), induces Bmp7 transcription." (PMID 30814954, 2019). "The Ewing sarcoma cell line TC32 has been injected into the yolk sac of Casper embryos and after 24–120 h of injection these cells were able to migrate into the tail, by a mechanism dependent on Y-box binding protein 1 (YB-1), via HIF1α expression." (PMID 39595017, 2024).
metastatic tumors (6 papers, 2022 to 2025). "HSD3B1 rs1047303 and YBX1 rs12030724 significantly impacted patients’ OS among those with non-metastatic disease at diagnosis and under AbA-based treatment for mCRPC." (PMID 39337362, 2024). "We analyzed the protein expression of MYC and YBX1 by immunohistochemistry in a tissue microarray of tissue cores from 32 RMS patients, including 17 primary tumors (12 FN and 5 FP) and 15 recurrent or metastatic tumors (8 FN and 7 FP) along with 5 muscle controls." (PMID 37345125, 2023).